HFE (homeostatic iron regulator)
Diseases named in the same sentence as HFE in open-access papers (continued):
Sharing a sentence is not in itself a finding about the gene and the disease.
breast carcinoma (10 papers, 2006 to 2025). "A recent study found an association between HFE C282Y and a higher risk of breast cancer, colorectal cancer, hepatocellular carcinoma, and total cancer." (PMID 31226389, 2019). "Our results suggest that HFE H63D mutation frequencies were increased in the breast cancer patients in comparison to those in the general population." (PMID 16503999, 2006). "Generally, FSLs offer germline testing for common, prevalent conditions, such as genotyping of common variants (e.g., factor V Leiden, HFE C282Y and H63D) and multigene panels for hereditary disorders that are limited to certain common diseases (e.g., breast cancer)." (PMID 33958748, 2021). "Also, a cohort of Lithuanian breast cancer patients revealed that the rs1799945 H63D variant of the homeostatic iron regulator gene, HFE, results in the substitution of aspartate for histidine at position 63 and is associated with anthracycline-induced cardiotoxicity." (PMID 37626782, 2023). "However, when compared to other actionable genotypes on ACMG or CDC tier 1 list, such as breast cancer related genotypes, HFE C282Y (+/+) can be considered a rather “benign” genotype with efficacious interventions." (PMID 41408552, 2025). "Overall allele frequency for breast cancer group of 88 women (71 sporadic and 17 familial), for HFE H63D was 22.2% whereas there were no HFE H63D-homozygotes in the group." (PMID 16503999, 2006). "In a study of breast cancer, a more favourable outcome was described in patients with low TFR1 and high HFE gene expression." (PMID 23991213, 2013).
hepatocellular carcinoma (9 papers, 2005 to 2023). A malignant tumor that arises from hepatocytes. "Tissue biopsies were analysed from 144 cases of hepatocellular carcinoma for HFE C282Y mutations; the data produced were compared with the frequency of HFE mutations in a large sample of the local population." (PMID 15929796, 2005). "In this population, we found that only a very small proportion of homozygotes for the HFE C282Y mutation developed hepatocellular carcinoma." (PMID 15929796, 2005). "Moreover, a meta-analysis study identified a statistically significant association between the HFE H63D polymorphism and hepatocellular carcinoma, especially in Asian and African populations." (PMID 33921027, 2021). "We have carried out a cross-sectional study to determine the proportion of diagnosed hepatocellular carcinoma patients who are homozygous for the HFE C282Y mutation; and to estimate the penetrance of this genotype with respect to hepatocellular carcinoma in East Anglia." (PMID 15929796, 2005). "Male HFE C282Y homozygotes were more likely to be diagnosed with hepatocellular carcinoma (odds ratio [OR] = 14, 95% confidence interval [CI] = 5–37)." (PMID 15929796, 2005). "Because of the need for more data to inform decisions about the value of population screening we have now collected a much larger cohort of hepatocellular carcinoma (HCC) cases (n = 144) for HFE genotyping." (PMID 15929796, 2005).
liver disease (9 papers, 2015 to 2025). "This study aims to evaluate the correlation of the HFE gene mutations on Egyptian CHC with liver disease progression and the risk of HCC development." (PMID 34582652, 2021). "In patients with liver diseases, different cutoffs for biochemical iron tests are expected than those established for the general population, with higher levels detected before testing HFE mutations." (PMID 25654085, 2015). "However, the appropriate time to search for HFE mutations in patients with liver diseases is still a challenge for clinicians, especially when other diagnoses are present." (PMID 25654085, 2015). "Importantly, they persist despite repeated negative evaluations for C-reactive protein (CRP) and erythrocyte sedimentation rate (ESR), homeostatic iron regulator (HFE) gene mutations, or hepatic disease." (PMID 41256943, 2025). "To test whether the minor increase in iron parameters seen in Pi*ZZ individuals may affect the development of Pi*ZZ-related liver disease, we crossbred Pi*Z-overexpressing mice with HFE knockouts (HFE-KO)." (PMID 31717526, 2019).
Alzheimer disease (8 papers, 2006 to 2025). A progressive, neurodegenerative disease characterized by loss of function and death of nerve cells in several areas of the brain leading to loss of cognitive function such as memory and language. "To date, the relationship between HFE mutations and Alzheimer’s disease needs further investigation." (PMID 35408967, 2022).
anemia (6 papers, 2008 to 2025). A reduction in the number of red blood cells, the amount of hemoglobin, and/or the volume of packed red blood cells. "Our findings could contribute to the further investigation of mechanisms involved in the pathophysiology and important gender-related involvement of the TMPRSS6 and HFE polymorphisms on anemia in ESRD patients." (PMID 30984307, 2019). "Additionally, our results highlight the important gender-related involvement of the TMPRSS6 and HFE polymorphisms on anemia in ESRD patients and could help further research to investigate whether primary disorder itself modifies patient's response to anemia." (PMID 30984307, 2019). "Two different pathogenic types of anemia have been examined from the aspects of iron status parameters and the SNPs of three genes (TMPRSS6 A736V, HFE C282Y, and HFE H63D)." (PMID 30984307, 2019). "The data indicate that HFE overexpression leads to the development of anemia in control mice." (PMID 30271947, 2018). "In cross-sectional analyses, adjusting for maternal blood lead level at delivery and child’s concurrent anemia status, the relationship between genotype (either HFE or TF) and blood lead level (at any age) was non-significant (data not shown)." (PMID 18795173, 2008).
beta thalassemia (6 papers, 2012 to 2020). Beta-thalassemia (BT) is characterized by deficiency (Beta+) or absence (Beta0) of synthesis of the beta globin chains of hemoglobin (Hb). "The G71D and H63D mutation of HAMP and HFE gene are frequently found in beta thalassemia major patients." (PMID 32588561, 2020). "The aim of this research work was to study the presence of G71D mutation of HAMP gene and H63D mutation of HFE gene in beta thalassemia major and minor group to check the association of these mutations with serum ferritin level of beta thalassemia patients." (PMID 32588561, 2020). "A Sri Lankan study on HFE gene analysis in 125 patients with thalassemia major in 2012 showed an allele frequency of 0% for C282Y and of 9.2% for H63D." (PMID 32641120, 2020). "We studied the presence of G71D mutation of HAMP gene and H63D mutation of HFE gene in beta thalassemia major and minor group to check the association of these mutations with serum ferritin level of beta thalassemia patients." (PMID 32588561, 2020). "This study aimed to detect the most common HFE gene mutations (C282Y, H63D, and S56C) in Egyptian beta- thalassemia major patients and their relation to patients iron status." (PMID 27335591, 2016). "In previous reports from different countries, the association between beta-thalassemia and the HFE gene mutation has been investigated." (PMID 25330520, 2014). "Notably, the negative association with the presence of hepatic iron accumulation was independent of demographic features, such as age and gender, and of other genetic factors (HFE mutations and the beta thalassemia trait)." (PMID 23144979, 2012). "However, differently from what was observed in the general population, TMPRSS6 genotype did not influence TS, which on the other hand was modulated by HFE mutations and the beta-thalassemia trait." (PMID 23144979, 2012).
Cognitive impairment (6 papers, 2006 to 2024). Abnormal cognition is characterized by deficits in thinking, reasoning, or remembering. "Our findings suggest that HFE polymorphisms greatly enhance susceptibility to lead-related cognitive impairment in a pattern consistent with allelelic dose." (PMID 17687449, 2007). "Even in the early stage of AD, the combination of Tf C2 and HFE C282Y has the ability to transport an excess of redox-active Fe2+, which induces mild cognitive impairment (MCI)." (PMID 30383537, 2018).
COVID-19 (5 papers, 2021 to 2025). A disease caused by infection with severe acute respiratory syndrome coronavirus 2. "In CD3+ lymphocytes from COVID-19 patients, protein–protein interactions (PPIs) between HPX, Tf, HFE, and Cp were associated with high confidence (0.7)." (PMID 36613462, 2022). "Further to which, the top two over-expressed genes of the “COVID-19-specific gene signature” are coiled-coil and C2 domain containing 2A (CC2D2A) and human homeostatic iron regulator or high FE2+ (HFE)." (PMID 33437935, 2021). "Here, we observe over-expression of CC2D2A, HFE, and ACO1 in COVID-19 infections and lower expression in non-COVID-19 previously circulating infections." (PMID 33437935, 2021).
Hypertension (5 papers, 2010 to 2023). The presence of chronic increased pressure in the systemic arterial system. "Because blood pressure and cholesterol level in blood could influence arterial stiffness, one might be concerned that treatment for hypertension and hyperlipidemia could alter any effect modification by HFE variants." (PMID 20478760, 2010). "An association between genetic variants in the genes HFE, HJV, BMP4 and arterial hypertension has been shown earlier." (PMID 35442992, 2022).
liver cancer (5 papers, 2005 to 2025). An epithelial or non-epithelial malignant neoplasm that arises from the liver. "Within HFE p.C282Y homozygous male participants, a polygenic score for liver cirrhosis was nominally associated with increased risk of liver cancer (OR, 1.48: 95% CI, 1.03–2.12; p = 0.04)." (PMID 35567766, 2022). "Other mutations such as rs738409-G (PNPLA3) and rs1800562-A (HFE) could also influence the observed association between serum cholesterol and liver cancer." (PMID 33808094, 2021). "HFE p.Cys282Tyr homozygous males have a 12-fold increased lifetime risk of primary liver cancer compared to those without HFE variants." (PMID 37067673, 2023). "If HCC cases have not been reported to the cancer registry or were not accurately classified (e.g. recorded as liver cancer not otherwise specified) then our calculation of the penetrance of these HFE mutations would be an under-estimate." (PMID 15929796, 2005). "Our results show that male HFE C282Y homozygotes were more likely to be diagnosed with HCC (OR = 14, 95% CI = 5–37); the HFE C282Y homozygous genotype could therefore be a significant cause of liver cancer." (PMID 15929796, 2005).
Parkinson disease (5 papers, 2006 to 2025). A progressive degenerative disorder of the central nervous system characterized by loss of dopamine producing neurons in the substantia nigra and the presence of Lewy bodies in the substantia nigra and locus coeruleus. "Accumulating evidence indicates that HFE mutations are associated with susceptibility to many clinical diseases, such as Parkinson's disease (PD), primary varicose veins and coronary heart disease (CHD)." (PMID 27657935, 2016).
thalassemia (5 papers, 2011 to 2022). An inherited blood disorder characterized by a decreased synthesis of one of the polypeptide chains that form hemoglobin. "Previous studies have described the prevalence of HFE gene mutations in the Iranian population, in patients with thalassemia, and in a group of diabetics." (PMID 22308152, 2011). "Data on the HFE gene variants in Sri Lankan patients with thalassemia have not been extensively studied." (PMID 35903164, 2022).
type 1 diabetes (5 papers, 2018 to 2023). "They found an increased risk of childhood diabetes Type I in children of mothers with iron supplementation or with common genetic variants in the HFE gene that are linked to high/intermediate iron stores." (PMID 34203528, 2021). "Importantly, maternal, but not fetal, human homeostatic iron regulator protein (HFE) genotypes, causing specific iron storage levels, were associated with offspring type 1 diabetes, potentially underlining the maternal dependency." (PMID 37892409, 2023).
type 2 diabetes (5 papers, 2011 to 2023). "We further validated the known association between HFE C282Y and type 2 diabetes which could be, at least partly, due to iron accumulation in the pancreas." (PMID 31226389, 2019). "Similarly, previous interaction findings for type 2 diabetes susceptibility genes, such as TCF7L2, GIPR, CAV2, and HFE, with other dietary factors were not replicated in the EPIC-InterACT study." (PMID 32722593, 2020).
autoimmune disease (4 papers, 2017 to 2023). A disorder resulting from loss of function or tissue destruction of an organ or multiple organs, arising from humoral or cellular immune responses of the individual to their own tissue constituents. "Furthermore, many HH patients are also afflicted by several immune defects and increased occurrence of autoimmune diseases that are linked to human homeostatic iron regulator protein (HFE) in the immune response." (PMID 32327961, 2020). "HFE mutations, the resulting iron imbalance, or both events may predispose HH patients or modify their response in the development of cancer, autoimmune diseases, and adaptive immunity to pathogens." (PMID 28474781, 2017).
coronary artery disease (4 papers, 2016 to 2024). "In a mendelian randomisation analysis, Gill et al30 recently found that higher genetically determined iron levels were associated with reduced risk of coronary artery disease (although separate data on HFE p.C282Y homozygotes were not modelled)." (PMID 30651232, 2019).
dementia (4 papers, 2021 to 2025). Loss of intellectual abilities interfering with an individual's social and occupational functions. "In females, only carriers of H63D HFE that also had diabetes had an increased risk of dementia, highlighting the importance of understanding the role of HFE variants in the context of disease states and other environmental factors." (PMID 38542306, 2024). "In summary, men with the HFE p.C282Y homozygous mutation developed substantially more marked brain iron deposition in dementia relevant brain areas." (PMID 33427739, 2021). "However, there are a few studies that may suggest that HFE variants affect one’s propensity for broader risk factors of dementia." (PMID 38542306, 2024).
iron-overload disease (4 papers, 2018 to 2024). "Genetic hemochromatosis is an iron overload disease that is mainly related to the C282Y mutation in the HFE gene." (PMID 30486249, 2018).
liver cirrhosis (4 papers, 2012 to 2022). "Thus the results of the study are not surprising, however they cannot serve as a complete source of information about the influence of the HFE gene mutations on the development of liver cirrhosis." (PMID 22550532, 2012). "Pooled analysis for the association between HFE C282Y, H63D genotype frequencies and the risks of NAFLD, liver cirrhosis, HCC." (PMID 27657935, 2016). "S4 Table presents the summarized characteristics and methodological quality of selected studies, and S5 and S6 Tables show the genotype distributions of the HFE C282Y and H63D polymorphisms in NAFLD, liver cirrhosis and HCC disease." (PMID 27657935, 2016). "Additional well-powered studies are required to confirm the effect of multiple HFE mutations (C282Y, H63D and S65C) on the susceptibility to different types of NAFLD, liver cirrhosis and HCC." (PMID 27657935, 2016). "An updated systematic review and meta-analysis was conducted to evaluate the potential role of HFE polymorphisms in the susceptibility to NAFLD, liver cirrhosis and HCC." (PMID 27657935, 2016). "Therefore, we performed an updated meta-analysis to better understand the genetic relationship between HFE mutations and the risks of HCC and liver cirrhosis." (PMID 27657935, 2016). "Furthermore, we found that the HFE mutations failed to increase the odds of developing liver cirrhosis." (PMID 27657935, 2016). "Our meta-analysis provides evidence that the HFE C282Y and H63D polymorphisms confer increased genetic susceptibility to NAFLD and HCC but not liver cirrhosis." (PMID 27657935, 2016).
osteoporosis (4 papers, 2017 to 2025). A condition of reduced bone mass, with decreased cortical thickness and a decrease in the number and size of the trabeculae of cancellous bone (but normal chemical composition), resulting in increased fracture incidence. "Osteoporosis was evident in 25% to 34% of patients with a genetic mutation of the HFE gene resulting in HFE-dependent HH, which is the most common form of HH." (PMID 39556493, 2025). "More recent studies using data from the UK Biobank found that patients with homozygous mutation in HFE (C282Y) showed that males with HFE-dependent HH have double the risk of developing osteoporosis, although a nonsignificant effect was observed among females." (PMID 39556493, 2025).
chronic hepatitis C (3 papers, 2018 to 2023). "Our results confirm the notion that HFE mutations may contribute to (but do not fully explain) hepatic iron accumulation in chronic hepatitis C." (PMID 37632052, 2023).
cryptogenic cirrhosis (3 papers, 2012 to 2016). "For instance, the polymorphisms of the HFE gene are not essential for cryptogenic cirrhosis in the southern Iranian population." (PMID 27657935, 2016). "Although hemochromatosis, and its pathophysiology were not understood until cloning of the HFE-gene, it has been known as a chronic liver disease for a long time, although it may be under-recognized due to the lack of specific symptoms and thus contribute to cases of cryptogenic cirrhosis." (PMID 22550530, 2012).
dilated cardiomyopathy (3 papers, 2010 to 2024). Cardiomyopathy which is characterized by dilation and contractile dysfunction of the left and right ventricles. "We confirm the lack of association between HFE polymorphisms and IHD in our material, as well as confirming the lack of association with dilated cardiomyopathy." (PMID 20670400, 2010).
Hepatic steatosis (3 papers, 2016 to 2025). Steatosis is a term used to denote lipid accumulation within hepatocytes. "For instance, five variants in or near TM6SF2, PNPLA3, HFE, APOE, and MTARC1 had comparably larger effects on HCC than on hepatic steatosis (p <0.05 by Cochran’s Q test), while HCC-associated variants in HSD17B13, KLF15, and TERT did not significantly associate with steatosis." (PMID 40823170, 2025). "While the role of HFE polymorphism in the occurrence of NAFLD still remains unclear, our findings may suggest that iron-overload and subsequent oxidative stress in HH could be due to the alteration of hepatic triglyceride metabolism associated with hepatic steatosis." (PMID 32680469, 2020).
ovarian carcinoma (3 papers, 2013 to 2024). A malignant neoplasm originating from the surface ovarian epithelium. "HFE, one of the selected target genes of hsa-mir-20a, has been found to be associated with immune response in GBM and ovarian cancer." (PMID 24521265, 2013). "Furthermore, lower expression levels of ACO1, HFE, IREB2, and MTF1 in iron regulation were associated with an advanced stage of ovarian cancer." (PMID 38186569, 2023). "The expression of HFE, MTF1, and BMP6 involved in iron regulation was associated with improved PFS in ovarian cancer, whereas the expression of HIF1A, GPI, and HAMP involved in this process was associated with poor PFS in ovarian cancer." (PMID 38186569, 2023). "Exploring the iron regulation in ovarian cancer, most genes integral to this process, like IREB2, HFE, BMP6, HMOX1, and ACO1, showed decreased expression compared to their normal tissue counterparts." (PMID 38186569, 2023).